IL2 (interleukin 2)
Diseases named in the same sentence as IL2 in open-access papers (continued):
Sharing a sentence is not in itself a finding about the gene and the disease.
depression (continued). "Lower lipopolysaccharide stimulated cell proliferation and phytohaemagglutinin stimulated or plasma cytokine IL-2 decreases should be potential monitoring indices in the depressive state assessment for major depressive disorder patients." (PMID 30314474, 2018). "Although we know IL-2 therapy induces depressive disorder, little is known on the molecular mechanisms exerted by IL-2 to trigger such disorder." (PMID 30662368, 2018). "In this analysis, model 1 included CES-D scores of depression and model 2 included the inflammatory mediators IL-2, IFN-y, and PGE2." (PMID 27316678, 2016). "Meanwhile, some studies found that in patients with severe depressive disorder, the activation of proinflammatory cytokines and inhibition of interferon-gamma, interleukin-2, and interleukin-4 were documented." (PMID 27955661, 2016). "Elevations in proinflammatory cytokines like prostaglandin E2 (PGE2), C-reactive protein (CRP), TNF-α, IL-1β, IL-2, and IL-6 have been reported in major depressive disorder and, at times, have shown a dose-response with severity of depression." (PMID 26550011, 2015). "In a clinical study, patients with depressive episodes demonstrated an increase in IL-6 levels, whereas patients with maniac episodes showed an increase in IL-2, IL-4, and IL-6 levels." (PMID 23497121, 2013). "A cluster of cytokines including interleukin-1 beta (IL-1β), IL-2, IL-6, interferon-gamma, and tumor necrosis factor alpha (TNFα) have been reported to correlate with depression symptoms." (PMID 21864357, 2011). "Depression of circulating lymphocytes and interleukin-2 production following mitogen stimulation has been observed after a fast of only 7 days." (PMID 22567271, 2011). "In agreement with our findings, previous studies in major depressive disorderreport that the elevation in IL-2 production during depressive state (Seidel etal." (PMID 18317531, 2007). "Statistically significant finding of cytokines in our research, as well as presence of cytokines IL-2 and IL-6 which are analyzed in relation to depression, confirms the existence of relationship between depression and BMS." (PMID 16864905, 2006). "Similarly, data from a cross-sectional study have shown that first-episode depression and recurrent depressive disorder are associated with lower serum concentrations of BDNF and higher IL-2 levels." (PMID 40133606, 2025). "IL-2’s potential to modulate immune responses while restoring T-regulatory cell balance offers an innovative avenue for addressing the inflammatory component of depression." (PMID 40002916, 2025). "Furthermore, one study identified an association between IL-2 levels and suicidal ideation in DN FE MDD patients, suggesting a potential link between IL-2 dysregulation and the severity or clinical features of depressive episodes." (PMID 41226404, 2025). "Furthermore, additional investigations have shown increased blood levels of IL-1β, IL-2, and IL-8 in individuals suffering from depression." (PMID 38877455, 2024). "The levels of tumor necrosis factor-alpha (TNF-a) interleukin-1 beta (IL-1b), and interleukin 6 (IL-6) were found to be associated with depression severity as measured by BDI II, while levels of Interleukin-2 (IL-2) were found to be correlated with anxiety measured by STAI-state." (PMID 37250694, 2023). "In addition, a higher risk of depression has been linked to higher levels of Interferon gamma (IFN-γ), Interleukin 2 (IL-2), TNF-α as pro-inflammatory cytokines, and inflammatory markers as C-reactive protein (CRP)." (PMID 37386551, 2023). "In addition to lowering cholesterol and increasing triglycerides, interleukin-2 inhibits melatonin release, which reduces brain serotonin, resulting in depression and suicidal tendencies." (PMID 36653784, 2023).
depression (continued). "The occurrence of depression in SLE patients may be predicted by decreased BDNF levels and the elevated levels of autoinflammatory factors (including IL-2 and IL-6) linked to depression, as well as their interaction with gut microbiome." (PMID 36506019, 2022). "In addition, activated inflammatory systems, including cytokines (IL-2 and IL-6), play a crucial role in the pathogenesis of depression." (PMID 36506019, 2022). "Interestingly, our results showed that IL-2 levels in the depression patients was significantly decreased at the baseline and increased after 2 weeks of active TMS treatment." (PMID 35722555, 2022). "Depression is accompanied by the changes in the levels of inflammatory and trophic factors, including interleukins (IL-1beta, IL-2, IL-6), interferon alpha (IFN-alpha), tumor necrosis factor alpha (TNF-alpha), C-reactive protein (CRP), and brain derived neurotrophic factor (BDNF)." (PMID 35455388, 2022). "We analyzed plasma IL-1β, IL-2, -6, -8, -10, TNF, kynurenine, tryptophan, serotonin, kynurenic- quinolinic- and picolinic acids and used mixed-effects models to assess the association between biomarkers and depression severity." (PMID 35078975, 2022). "In addition, exercise training can block the proinflammatory factors IL-2 and IL-6, accelerate the transformation of microglia into M2, regulate gut flora, and lower the incidence of depression following stroke." (PMID 36389714, 2022). "In order to demonstrate these hypotheses, IL-2 was selected to treat a popular rodent model of depression induced by chronic unpredictable mild stress (CUMS), simulating long-term pressures in human beings." (PMID 36430328, 2022). "Low-dose IL-2 administration was found to attenuate inflammatory responses and anxiety-like behaviors in patients with autoimmune diseases, as well as attenuate depression-like behaviors in a depression model of olfactory bulbectomized rats." (PMID 36430328, 2022). "Besides, the baseline TNF-α level was significantly higher and IFN-γ, IL-4, and IL-2 were lower in patients with depression compared with the HC group." (PMID 35722555, 2022). "An early study reported that elevated serum IL-2 levels in patients with major depression compared with controls may be a compensatory response to NK cell activity." (PMID 36506019, 2022). "For example, a study, using SEM, proposed a model that cortisol (as an indicator of Hypothalamic pituitary adrenal) predicts depression, which predicts circulating pro-inflammatory cytokines (IL-2, IL-6, TNF-α) In patients diagnosed with chronic fatigue syndrome (CFS)." (PMID 36210450, 2022). "The Traditional Chinese Medicine Systems Pharmacology Database (TCMSP), the Analysis Platform, DrugBank, and other databases were analyzed using data mining, and the results show that the active components of HP and depression are linked to targets such as TNF-, IL-2, TLR4, and so on." (PMID 36556951, 2022). "IL-2 is a key cytokine in T lymphocytes activity, the function of which is disturbed in depression." (PMID 33255237, 2020). "Depressive disorders is characterized by inflammation, as indicated by elevated concentrations of pro-inflammatory cytokines (e.g., IL-1β, IL-2, and IL-6), and it is characterized by cell-mediated immune (CMI) activation and Th1-like response, as suggested by increased production of IFN-γ." (PMID 31215856, 2020). "In addition, immunotherapy with IL-2 can produce depressive symptoms, which in turn are reduced by the administration of antidepressants, supporting the role of IL-2 in depressive disorders." (PMID 30662368, 2018). "There is substantial evidence showing that IFN-γ and IL-2 play important role also in depression." (PMID 26403459, 2016).
depression (continued). "Further evidence in support of increased kynurenine pathway activation and subsequent tryptophan depletion in depression stems largely from the study of cytokine-induced depression, which occurs in 30% to 50% of medically ill patients being treated with IL-2 or IFN-α for cancer and Hep C." (PMID 26775294, 2016). "Prospective studies will need to confirm whether measuring IL-2 and IFN-γ can identify COPD patients at risk of depression." (PMID 26403459, 2016). "Depression is associated with higher levels of IL-1β, IL-6, IFN-γ and TNF-a schizophrenia has been find to exhibit increased concentrations of IFN-γ, IL-2 and IL-6 whereas IL-2, IL-6,IL-8 and IFN-γ were found to be overproduced during BD." (PMID 27598205, 2016). "Neurologic side effects of IL-2 have been previously reported to present as lethargy, anxiety, vivid dreams, confusion, sleep disturbance, decreased concentration, mood swings, hallucinations, depression, and coma." (PMID 26557408, 2015). "Another indication that inflammation and depression are linked comes from clinical observations in which therapeutic administration of the proinflammatory cytokines interleukin-2 and interferon-α to cancer or hepatitis C patients resulted in depression in up to half of these patients." (PMID 23935246, 2013). "In addition, therapeutic administration of the cytokine IL-2 and interferon-á has been shown to lead to depression in patients." (PMID 22860054, 2012). "The finding of increased IL-12 in patients with major depression,together with increased IL-2, may be considered as additional evidence foractivation of Th1-type immune response during major depression." (PMID 18317531, 2007). "Chronic systemic inflammation in COPD may also contribute to neuroinflammatory processes that underlie depression, and elevated levels of pro-inflammatory cytokines such as IL1β, IFN-γ, IL-2, and tumor necrosis factor (TNF) have been observed in patients suffering from both COPD and depression." (PMID 41008474, 2025). "Moreover, IL-2 levels were significantly higher in the COPD group with comorbid depression." (PMID 37048736, 2023). "According to the hypothesis, the present study, for the first time, demonstrated that the intraperitoneal injection of low-dose IL-2 markedly treated depression- and anxiety-like behaviors by restoring the imbalance between Treg and Th17 in the hippocampus of CUMS mice." (PMID 36430328, 2022). "The elevated expression of the inflammatory cytokines IL-2 and IL-6 in the intestine and brain tissues of patients with post-stroke depression decreased following exercise intervention, which may be related to the enhanced expression of Lactobacillus and Bifidobacteria." (PMID 36389714, 2022). "In the active rTMS group, the serum levels of CRP-hc and IL-2 significantly changed at week 2, and the change last through the 12 weeks period, which were not seen in the sham-rTMS group, suggesting that rTMS can change serum inflammatory cytokine levels in patients with depression." (PMID 35722555, 2022). "Furthermore, IL-2 treatment exerted effects of anti-anxiety and anti-depression, such as increasing the number of entries into (p = 0.039) and the time spent (p = 0.0061) on the open arms, as well as decreasing the immobility time in the suspension tail test (p = 0.0443)." (PMID 36430328, 2022). "IL-2 increase was not linked to EDs, but to the interaction of depression and BMI." (PMID 31450770, 2019). "Interestingly, IL-2 is known to increase the suppressive abilities of T regs, hence, the reduction of IL-2 which is seen in some studies of depression may reduce the anti-inflammatory effects of T regs." (PMID 23382717, 2013). "Elevated IL-6 levels are found in both COPD and depression, with IL-6, IFN-γ, and IL-2 involved in producing symptoms of depression." (PMID 40724725, 2025).
depression (continued). "Conversely, in males, inflammation was inversely associated with depression severity, with protective effects from regulatory mediators (IL-2, IL-4, IL-6, IL-15, LIF, TNF-α, β-NGF) against depression." (PMID 40305313, 2025). "Escitalopram can reduce the levels of pro-inflammatory cytokines—IL-1β, IL-1ra, IL-2, IL-4, IL-6, IL-8, IFN-y, TNF-α in the serum of patients suffering from depression, while simultaneously increasing the level of anti-inflammatory IL-10." (PMID 41302150, 2025). "Taken together, these findings highlight the significant role of inflammation, particularly mediated by cytokines like IL-2, IL-6, and IFN-γ, in the pathogenesis of both COPD and depression." (PMID 40724725, 2025). "Most present studies mainly focused on exploring the relationship of IL-1b, IL-2, IL-6, and TNF-a, with depression." (PMID 40530060, 2025). "A recent study found elevated levels of IL-2, IL-6, and interferon-gamma (IFN-γ) in patients suffering from co-morbid COPD and depression compared to healthy controls, though the implications of these findings remain uncertain." (PMID 37754012, 2023). "The treatment options in cancer can also affect the development and manifestations of depressive disorder, for example, when interfering with IL-2, IL-6, IFN-α or steroids which are well-known depression inducers." (PMID 36787313, 2023). "Studies have reported that IL-6, TNF-α, CRP, YKL-40, IL-17, IL-1β, CCL2, IL-2, and IL‐8 are related to worse cognitive function or cognitive deterioration, while CRP, TNF-α, sIL-2R and CCL2 reflect severe symptoms of depression and anxiety." (PMID 36739284, 2023). "In particular, IL-1β, IL-2, IL-6, TNF-α and IFN-γ are reported to be involved in cytokine-induced depression." (PMID 36045388, 2022). "The most commonly involved inflammatory markers observed in the pathogenesis of both depression and Psoriasis are IL-6, IL-17, IL-13, IL-23, IL-10, IL-1β, and type A cytokines (TNF-α, IL-2, INF-γ) through Th1 and Th17 lymphocytes mediated processes." (PMID 34183985, 2021). "Increasing levels of proinflammatory mediators such as IL-1, IL-2, IL-6, and TNF-α have been observed in patients with depression." (PMID 33513891, 2021). "Si-Ni-San reduces the release of inflammatory factors IL-1β, IL-6, IL-2, and TNF-α in the peripheral fluid of patients with post-stroke depression and regulates the over-activation of the HPA axis, thereby exerting an antidepressant effect." (PMID 33790789, 2021). "Activation of Th1 and Th17 cells, which leads to an increased production of IL-2, IFN γ, and IL-17, was also observed in depression." (PMID 30092066, 2018). "This suggests that the change in inflammatory mediators IL-2, IFN-y, and PGE2 explains an additional 39 % of the variability in the change in sensory neuropathic pain scores when the change in CES-D scores of depression has been statistically controlled for." (PMID 27316678, 2016). "Changes in IFN-γ and IL-2 levels and their important role for development and progression of COPD and depression have been already reported by others." (PMID 26403459, 2016). "In this study, we aimed to explore the role of IL-2, IL-4, IL-12, TNF-α, TGF-β1, and MCP-1 in major depression and to investigate the effects of sertraline therapy." (PMID 18317531, 2007). "The mean levels of HDRS (P < .001), IL-2 (P < .001), IL-12 (P <.001), TNF-α (P < .001), and MCP-1(P < .001) were significantlyhigher in patients with major depression than in controls." (PMID 18317531, 2007). "However, the majority of existing epidemiological studies have primarily examined relationships between interleukin-1b (IL-1b), interleukin-2 (IL-2), interleukin-6 (IL-6), tumor necrosis factor-alpha (TNF-a), and other inflammatory factors and depression." (PMID 40530060, 2025). "Additionally, patients with major depression showed significantly elevated levels of proinflammatory cytokines (TNF-a, IL-2, IL-12) after sertraline use." (PMID 40283042, 2025).
depression (continued). "Paraclinical evaluation, such as reduced FEV1 and elevated CAT scores, has been identified as an aggravating factor, accompanied by laboratory findings of high inflammation factors such as IL1 beta, IFN-γ and IL-2, and TNF, would be present in patients with both COPD and depression." (PMID 41008474, 2025). "In SLE patients with depression, the abundance of the genus Subdoligranulum was decreased compared to the healthy controls, and it showed a negative correlation with IL-2 and IL-6 at the genus level." (PMID 39457690, 2024). "Unipolar depression (Major Depressive Disorder—MDD) has generally been found to stimulate a pro-inflammatory Th1 response (IL-1, IL-2, soluble IL-2 receptor (-sIL-2R), IL-6, C-Reactive Protein (CRP), TNF-α, and IFN-γ), with a subsequent increase in tryptophan catabolites (the kynurenine pathway)." (PMID 37510730, 2023). "At 24 h, elevated IL-2 (p = 0.001) and lower IL-6 (p = 0.035) and IL-17a levels (p = 0.007) ass. with severe PCS at 1 week (p = 0.001).At 6 months, elevated IL-10 ass. with depression (p = 0.004) and PTSD (p = 0.001)." (PMID 37251220, 2023). "Moreover, compared with healthy controls, a higher level of IL-2, IL-6, and interferon (IFN)-γ was reported in patients with comorbid depression in COPD." (PMID 37048736, 2023). "Patients with depression disorder exhibit a chronic inflammatory state which is characterized by elevated serum levels of pro-inflammatory cytokines, including TNF-α, IL-1β, IL-2, IL-6, IL-12, and decreased levels of anti-inflammatory cytokines, such as IL-10, compared to controls." (PMID 37273278, 2023). "Furthermore, the long-term improvement of depressive symptoms in the patients was significantly correlated with the change of IL-2 levels, in supporting of the pathological role of IL-2 in the development and TMS treatment of depression." (PMID 35722555, 2022). "It is possible that the IL-2 effects on depression-like changes were not via CORT or that the treatment duration was not enough to significantly change CORT." (PMID 36430328, 2022). "The effect of the extract on the role of inflammatory mediators (specifically IL-2, IL-6, IL-8 and TNF-ɑ) in aggression and depression could be considered for future research." (PMID 36386158, 2022). "The NPC patients with depression showed significantly higher levels of IL-1β and IL-2 relative to healthy comparisons, while patients without depression only had higher IL-2 than healthy subjects (p<0.05 after FDR correction)." (PMID 34900691, 2021). "Decreases in IL-2, IL-4 productions, and CD4 percentage were strictly independent of anxiety and depression rates, as there were no more significant differences between the two groups given the HADS scores for anxiety and depression." (PMID 34987425, 2021). "Most of the inflammatory markers involved in Psoriasis (TNF-α, IL-2, IL-6, IL-23, IL-1β, IL-10), and increased serotonin transporters (5-HTT) were also found in the pathogenesis of depression, showing the immune-inflammatory linkage between psoriasis and major depression." (PMID 34183985, 2021). "BMI (underweight = 3.9 ± 2.5; normal-weight = 10.3 ± 2.3; obesity-1/class I obesity = 4.1 ± 2.3; obesity-2/class II/III obesity = 2.4 ± 1.4) and depression were not significant for IL-2." (PMID 31450770, 2019). "Our results seem to resume and confirm these findings: we found that serum levels of IL-2 were not significantly influenced by ED diagnosis or BMI, but by the interaction effect of depression and BMI." (PMID 31450770, 2019). "In addition, resveratrol supplementation reduces levels of pro-inflammatory cytokines (IL-1β, IL-2, IL-4, IL-6, TNF-α) in animal models of depression." (PMID 30200269, 2018). "In addition, the positive relationship observed between IL-2 and ACTH has been documented to play a role in depressive disorders." (PMID 30405010, 2018).